MYC (MYC proto-oncogene, bHLH transcription factor)
Diseases named in the same sentence as MYC in open-access papers (continued):
Sharing a sentence is not in itself a finding about the gene and the disease.
colon carcinoma (continued). "Using TOPFlash/FOPFlash ratio to examine the effect of MYC on the activity of the WNT pathway, we found that DLD1 colon cancer cells transfected with TOPFlash reporter vector displayed constitutive TOPFlash activity that was reduced by treating cells with the inhibitor of the WNT pathway ICG-001." (PMID 31623618, 2019). "Importantly, siRNA-mediated inhibition of MYC in parental RKO cells and a second colon cancer cell line, HCT116, confirmed these observations." (PMID 31455158, 2019). "Cytolytic-high colon tumors on the other hand, were characterized by recurrent deletions at loci 1p35.3 (PIK3CD, TP73, miR34a), 6p25.3 (FOXC1), and 21q11.1 (Let-7c), and amplifications at loci 8q24.21 (MYC) and 20q13.12 (MMP9)." (PMID 31429779, 2019). "However, our results did show that the inhibitory effect of 5‐Aza on MYC, SUZ12, and KRAS is at least partially achieved by miR‐487b in colon cancer cells." (PMID 30791232, 2019). "Butyrate has been shown to downregulate Wnt activity in CC531 rat colon carcinoma cells by reducing the expression of 4 Wnt target genes that are upregulated in CRC [CCND1, c-MYC, FOSL1, and follistatin (FST)], but it has also been shown to induce Wnt signaling leading to stimulated apoptosis." (PMID 28077379, 2017). "Interestingly, other studies reported that MYC, by binding to CCAT1 promoter, induces CCAT1 transcription in colon cancer and gastric carcinoma, suggesting the existence of a positive feedback loop between CCAT1 and MYC mediated by let-7 decoy." (PMID 29147648, 2017). "HER3 has been involved in intrinsic resistance to MEK inhibition also in KRAS mutant lung and colon cancers and it has been found that MEK inhibition by selumatenib results in MYC-dependent transcriptional up-regulation of HER3, which is responsible for intrinsic drug resistance." (PMID 29312543, 2017). "Still, these effects are clearly cell type dependent as CIP2A depletion did not affect AKT phosphorylation in various colon cancer cell lines whereas it potently inhibited c-MYC expression 12,34." (PMID 25663244, 2015). "We concluded that HUWE1 is requiredfor activation, but not repression, of MYC target genes in colon carcinoma cells." (PMID 25253726, 2014). "For example, ChIP-seq in LS180 colon cancer cells indicated VDR binding sites 139, 146 and 335 kb upstream of the MYC TSS, while ChIP-qPCR in RWPE-1 normal human prostate cells suggested VDR binding 1.3 kb upstream of the gene’s TSS and at site 1 (2.7 kb downstream of the TSS)." (PMID 24202443, 2013). "These miRNAs have been shown to mediate the proangiogenic effect of MYC by decreasing the THBS1 (particularly for miR-19a) and CTGF mRNA (particularly for miR-18a) half-life, thereby promoting tumor growth in vivo in a mouse colon carcinoma model." (PMID 22383169, 2012). "This analysis clearly indicates that the chromatin loops between distal enhancers and the MYC promoter are not restricted to colon cancer cells." (PMID 21533051, 2011). "In considering this mechanism, it is important to note that, similar to an earlier study, the recent studies did not observe differential MYC expression in colon tumors based on 8q24 genotypes." (PMID 21129217, 2010). "Additional findings supporting this mechanism included reduced colon tumor formation in muscarinic agonist-treated mice lacking intestinal epithelial cell βPix expression and reduced MYC, CCND1 and PTGS2 gene and protein expression in colon adenocarcinomas resected from those mice." (PMID 39493347, 2024).
colon carcinoma (continued). "Furthermore, we have identified significant upregulation of key transcription factor interactions in colon cancer patients, including the apoptotic regulation facilitated by E2F1, MYC, and MYCN, as well as activation of the BCL-2 protein family facilitated by TP73." (PMID 37398471, 2023). "To examine whether elevated CREPT level correlates to the expression of STAT3-downstream genes, we analysed the messenger RNA (mRNA) levels of several key genes including c-MYC, CCND1 and Bcl-XL in breast and colon cancers from The Cancer Genome Atlas RNA-sequencing database." (PMID 33531691, 2021). "In addition, c-MYC downregulation was reported to lower the proliferation and reduce glucose consumption, lactate production, and ATP production to depress glycolytic metabolism in DLD-1 and SW480 colon cancer cells, which was concordant with our results." (PMID 34921134, 2021). "Importantly, Lnc-EPIC1 siRNA (by si-Lnc-EPIC1-s1) or ectopic Lnc-EPIC1 overexpression failed to alter functions of MYC KO colon cancer cells." (PMID 33170148, 2020). "We found that RNF8 had a positive relationship with MYC in colon cancer but not in normal tissue." (PMID 32549753, 2020). "Because the activity of both MYC and the WNT pathway are profoundly involved in colon cancer, we examined the 41 pairs of normal/tumor colonic tissues deposited in the TCGA database for the expression of LEF1 and other genes upregulated by MYC in our RNA-seq dataset." (PMID 31623618, 2019). "Like c-MYC and cyclin D1, ITF-2 functions as an oncogene when deregulated in human colon cancer or ovarian cancer, although other studies have reported that the inactivation of ITF-2 may play a role in early gastric carcinoma progression or in the colonic adenoma to carcinoma transition." (PMID 28574827, 2017). "To determine whether c-MYC is involved in 5-FU resistance, we investigated the effect of c-MYC overexpression or knockdown on the survival rate following 5-FU treatment in human colon cancer cells." (PMID 25689483, 2015). "Additionally, this gene is a positive regulator of Wnt signaling, regulates the MYC oncogene, represses the cell cycle inhibitors CDKN2C/CDKN2D, and is a transcriptional driver of various oncogenes, contributing to the progression of colon cancer and other cancer types." (PMID 35992833, 2022). "Furthermore, the sensitivity of LoVo colon cancer cells to DDP, oxaliplatin, 5-Fu, and paclitaxel was distinctly enhanced, P-gp expression was authentically declined, and SMAD4 expression was noticeably augmented subsequent to OLR1 knockdown, which was reversed by further overexpressing c-MYC." (PMID 34921134, 2021). "The results of the present experiment contrasted with a previous study demonstrating that difluorinated-curcumin, a curcumin analogue, could significantly inhibit MYC expression in chemoresistant colon cancer cells, while curcumin could not exert such an effect." (PMID 30987250, 2019). "Unlike its role in colon cancer, our data thus do not imply HUWE1 as important regulator of MYC activity in MM." (PMID 33116152, 2020). "Importantly, most of WNT pathway genes induced by MYC, including DVL1, LEF1, RUVBL1, and RUVBL2, were also upregulated in tumor tissues when compared with the normal tissues from the same patients, suggesting that these genes may play a major role in colon cancer cells." (PMID 31623618, 2019). "As opposed to MYC, MAX levels were not consistently altered in colon cancer patient samples." (PMID 31623618, 2019). "It remains unknown whether CDK8 controls MYC phosphorylation directly or indirectly, however MYC has not been reported to be a substrate for CDK8 in human colon cancer cells." (PMID 30693281, 2018).
colon carcinoma (continued). "HuR-containing exosomes derived from colon cancer cells are up-taken by the human nontumorigenic lung epithelial BEAS-2B cells, which promote their migration and proliferation through the stabilization c-MYC transcripts and a decreased accumulation of the CDK inhibitor p21." (PMID 36831450, 2023).
neuroblastoma (433 papers, 1997 to 2026). Neuroblastoma (NB) is the most common solid, extracranial childhood tumor. "The adrenergic II pre-neuronal-like program was also observed in multiple other datasets and the “neuroblastoma-MYC” (high-risk) program formed a dense hub, with similar programs recovered in high-risk (both MYC and MYCN overexpressing) tumors in all datasets." (PMID 38898465, 2024). "MYC deficiency promotes lipid droplet accumulation in human neuroblastoma cells, and increases palmitate uptake and oxidation, and neutral lipid storage in human alveolar lung cancer cells." (PMID 38272231, 2024). "The administration of DFMO, a selective inhibitor of ODC, has been shown to be an effective strategy for the inhibition of both the occurrence and progression of MYC-associated Neuroblastoma." (PMID 38049863, 2023). "High-risk neuroblastomas are frequently driven by either N-MYC or c-MYC upregulation and have an extremely poor prognosis with 5-year overall survival of ~50%." (PMID 37973789, 2023). "Independent of genomic amplification, overexpression of N-MYC or c-MYC associates with the worst outcomes in neuroblastoma." (PMID 37973789, 2023). "The complex regulation of both signaling pathways in neuroblastoma and the resulting consequences for differentiation and metastasis, suggests a close association of the MYC and HIF signaling pathways in neuroblastomas." (PMID 37361539, 2023). "MYC overexpression led to a greater than 85% loss of global transcriptional oscillation in neuroblastoma and osteosarcoma cell lines." (PMID 37639465, 2023). "Together with HIF-1α, another transcription factor associated with poor neuroblastoma prognosis, MYC proteins are known to affect mitochondrial biogenesis and metabolism." (PMID 37973789, 2023). "It has been shown that MYC amplified tumors are associated with suppressed immune cell infiltrates in neuroblastoma and melanoma models." (PMID 36304306, 2022). "We have shown that treatment of MYC-driven neuroblastoma cells with CX-5461 and Halofuginone causes down-regulation of MYC and MYCN proteins and growth suppression MYC-driven neuroblastoma cell lines in vitro and preclinical models." (PMID 35053227, 2022). "Neuroblastoma cell lines with intermediate MYCN or MYC levels caused by gene translocations are known to exist." (PMID 35484422, 2022). "Genomic amplification of the MYC oncogene family member MYCN characterizes a subset of high-risk pediatric neuroblastomas." (PMID 33525507, 2021). "The presence of MYCN amplifications (MYC-Gain) automatically classifies neuroblastoma as high-risk and patients with this amplification are treated more intensely to increase the probability of overall survival." (PMID 34458583, 2021). "Together, these data reveal that indisulam induces a complete and durable antitumor response in different MYC-driven high-risk neuroblastoma models." (PMID 34788094, 2021). "MYC was previously implicated in different ALK dependent malignancies including non-small cell lung cancer neuroblastoma and ALK+ ALCL." (PMID 33310759, 2021). "High-risk, MYC-amplified or MYC-overexpressing neuroblastomas present poor prognosis and show elevated expression of PARP-1 and PARP-2." (PMID 34201047, 2021). "Whereas MYCN is amplified and highly expressed in about one-third of high-risk neuroblastomas, MYC is highly expressed in a distinct subset of Stage 4 neuroblastomas that have similarly aggressive clinical behavior." (PMID 33425720, 2020). "We noted that these data show that c-MYC overexpression causes resistance to 13-cisRA in neuroblastoma cell lines." (PMID 32409685, 2020).
neuroblastoma (continued). "High c-MYC protein is seen in 11% of neuroblastoma at diagnosis (MYC genomic amplification seen in 1%) and has been associated with a poor clinical outcome." (PMID 32409685, 2020). "Using MYC target database, results showed that MYC pathway activity was associated with the poor outcome of neuroblastoma." (PMID 32593299, 2020). "Expression of OCT4, MK2, and c-MYC was higher in progressive disease relative to pre-therapy neuroblastomas and was associated with inferior patient survival." (PMID 32409685, 2020). "A recently defined subset of high-risk neuroblastoma tumors that lack MYCN amplification overexpress the MYC protein and have a poor prognosis comparable to those with amplified MYCN." (PMID 32211329, 2020). "Recently, PRMT5 was found to associate with aberrant MYC function in various cancers including brain tumors such as glioblastoma and neuroblastoma." (PMID 31694585, 2019). "Further, the rate-limiting enzyme of polyamine synthesis ODC-1 is a direct downstream target of MYCN (and c-MYC), directly linking deregulation of polyamine metabolism to high-risk neuroblastoma, often characterized by MYCN amplification (reviewed in66)." (PMID 29968769, 2018). "NBT treatment decreased the expression of a neuroblastoma-derived MYC (MYCN) and multidrug resistance-associated protein 1 (MRP1) as well as downregulating Akt, GSK3β, and β-catenin." (PMID 30486290, 2018). "Regulation of the MRP1 gene at the 5′ untranslated promoter region is associated with various transcription factors, including neuroblastoma-derived MYC (MYCN)." (PMID 30486290, 2018). "In our previous study, MYC protein overexpression was shown to be associated more with rather Low- or Intermediate-MKI than High-MKI in neuroblastomas." (PMID 29464082, 2018). "Genomic analyses in neuroblastoma tumors have shown that MYC mutations are present in about 40% of high risk tumors that show poor prognosis." (PMID 29419804, 2018). "For example, a variant in MAX, an essential interacting partner of MYC, was identified in a patient with neuroblastoma." (PMID 30455982, 2018). "The association between activating ALK mutations and MYC or MYCN is observed in other malignancies including neuroblastoma and anaplastic large cell lymphoma (ALCL)." (PMID 29507657, 2018). "MYCN is deregulated through genomic amplification in ~40% of high-risk neuroblastomas, while MYC is frequently deregulated in a high proportion of the remainder." (PMID 29799508, 2018). "MYCN and MYC play a crucial role in determining the malignancy of unfavorable neuroblastomas, whereas high-level expression of the favorable neuroblastoma genes is associated with a good disease outcome and confers growth suppression of neuroblastoma cells." (PMID 24173829, 2014). "MYCN and MYC play a crucial role in determining the malignancy of unfavorable neuroblastomas, whereas high-level expression of favorable neuroblastoma genes is associated with a good disease outcome and confers growth suppression of neuroblastoma cells." (PMID 24173829, 2014). "Differences in MYCN/c-MYC target gene expression are associated with distinct neuroblastoma subtypes and clinical outcome." (PMID 18851746, 2008). "High MYCN/c-MYC target gene expression is a hallmark of malignant neuroblastoma progression, which is predominantly driven by c-MYC in stage 4-non-amplified tumors." (PMID 18851746, 2008). "Thereby, oncogenic expression of MYC has been shown to dampen the expression of activating NK cell receptors in high-risk neuroblastoma, indicating that MYC expression may serve as a biomarker for NK cell therapy." (PMID 37723317, 2023). "ODC1 is a direct target of MYC proteins and is associated with poor survival in neuroblastoma." (PMID 37760568, 2023).
neuroblastoma (continued). "Indeed, AHCY is directly regulated by MYC proteins and like these, associated with poor prognosis of neuroblastoma patients." (PMID 36870971, 2023). "High MYCN/c-MYC target gene expression is a hallmark of malignant neuroblastoma progression." (PMID 37361539, 2023). "Finally, a recent report linked activation of the MYC paralogue MYCN in neuroblastoma to dependence on cysteine import and synthesis, needed to produce glutathione and avoid ferroptotic cell death." (PMID 37158102, 2023). "The occurrence of MYCN amplification in approximately 20% of neuroblastomas, which correlates with high-risk disease and poor prognosis, further underscores the importance of MYC and HIF signaling pathways in these adrenal neoplasms derived from the neural crest." (PMID 37361539, 2023). "Strikingly, DOXY-mediated inhibition of mitochondrial translation led to a dose-dependent downregulation of these transcription factors, pointing to a novel therapeutically promising approach for inhibiting MYC proteins in multidrug-resistant high-risk neuroblastoma." (PMID 37973789, 2023). "Interestingly, gene set enrichment analysis (GSEA) revealed OXPHOS (oxidative phosphorylation) as the most prominently upregulated hallmark pathway in MYCN-amplified neuroblastoma cells, which is associated with an upregulation of the MYC-targeted pathway." (PMID 35805002, 2022). "Finally, inhibition of CDK7, a transcriptional cyclin-dependent kinase which functions downstream of MYC and is MYC’s 10th-ranked correlation, causes marked regression of aggressive, MYC-driven neuroblastomas in mice." (PMID 33328249, 2021). "Also, single-copy high-risk neuroblastomas frequently show high expression of the MYCN homolog c-MYC." (PMID 30542116, 2019). "Neuroblastoma may be especially responsive to DFMO treatment because MYC mutations and increased ODC activity are so prevalent in this type of cancer." (PMID 29419804, 2018). "A connection between ALK and MYC has been observed in neuroblastoma, where ALK gain-of-function mutations are more frequent in MYCN amplified tumors and activation of full length ALK increases mRNA, protein expression, and transformation potential of MYCN in neuroblastoma cell lines." (PMID 29507657, 2018). "In addition, these genes were predicted to be under the transcriptional control of MYCN/MYC regulatory network making them potential therapeutic targets in high-risk neuroblastoma." (PMID 26497213, 2015). "The compounds, either alone or in combination, caused death in the majority of MYCN-amplified cells, suggesting that clinically viable derivatives of these compounds could be used to treat high risk neuroblastomas and other tumors driven by MYC." (PMID 25477524, 2015). "In this study, we asked whether distinct transcriptional MYCN or c-MYC activities are associated with specific neuroblastoma phenotypes." (PMID 18851746, 2008). "Our data show that markers of increased MYCN/c-MYC activity are consistently represented in these classifier gene lists, indicating that a gene expression-based classifier that reflects MYCN/c-MYC function should make an attractive tool for neuroblastoma classification and risk prediction." (PMID 18851746, 2008). "In neuroblastoma (NB), amplification of the MYCN oncogene and over-expression of MYC characterize approximately 40% and 10% of all high-risk NB cases, respectively." (PMID 37760568, 2023).